CD38 (CD38 molecule)
Diseases named in the same sentence as CD38 in open-access papers (continued):
Sharing a sentence is not in itself a finding about the gene and the disease.
COVID-19 (continued). "In summation, in all cases, Treg subgroups were central parts of the top 5 most severity-associated (Ki67+CD38+: critical COVID-19, naïve Tregs and CM-like Treg: moderate COVID-19) or sex-associated (cTfr: female patients, Ki67+CD38+: male patients) cellular populations in COVID-19." (PMID 36669118, 2023). "Understanding this intricate balance in CD38+HLA-DR+ T cells is crucial for developing immunomodulatory strategies in COVID-19." (PMID 40370439, 2025). "We identified the selective expansion of CD38+HLA-DR+ T cells as a novel prognostic indicator for COVID-19 outcomes." (PMID 40370439, 2025). "The relationships between the prevalence of CD38+HLA-DR+ T cells and clinical indicators in COVID-19 patients were first investigated." (PMID 40370439, 2025). "The high similarity and intricate interplay between CD38+HLA-DR+ T cells and Tregs in COVID-19 highlights the complexity of immune dysregulation." (PMID 40370439, 2025). "In conclusion, the activation and exhaustion of CD38+HLA-DR+ T cells in COVID-19 represent a complex equilibrium central to the disease’s pathogenesis." (PMID 40370439, 2025). "During acute COVID-19, cell clusters emerged co-expressing several T cell activation markers including HLA-DR, granzyme B, and CD38." (PMID 41310351, 2025). "It has been demonstrated that activated CD8+HLA-DR+CD38+ T cells in a mild case of COVID-19 significantly expand following symptom onset, which reached their peak frequency of 12% of CD8+ T cells on day 9 after symptom onset and contracted thereafter." (PMID 40573882, 2025). "Our findings highlight the critical role of the CD38+HLA-DR+ T cell subset in predicting the early prognosis of COVID-19 patients." (PMID 40370439, 2025). "For example, T cells expressing activation markers such as CD38 and HLA-DR have been observed in COVID-19 patients, suggesting functional impairment and immune dysregulation associated with disease severity." (PMID 40370439, 2025). "Serum levels of 12 inflammatory cytokines were analyzed in COVID-19 patients, comparing the CD38+HLA-DR+ Thi and the CD38+HLA-DR+ Tlow group, divided by median (10.01%)." (PMID 40370439, 2025). "Previous studies have shown that elevated expression of CD38 and HLA-DR or CD38 and Ki67 in T cells is related to a poor prognosis and greater disease severity in COVID-19 patients." (PMID 40573882, 2025). "In our cohort, the frequency of TCD8+HLA-DR+CD38+ cells washigher in COVID-19 patients than in healthy controls, whileHLA-DR+CD38+ cells were notably decreased." (PMID 41259458, 2025). "Compared to healthy controls and bacterial pneumonia patients, we observed elevated percentages of CD38+HLA-DR+ T cells in COVID-19 cases (0.94%, 2.16% vs. 10.01%, respectively, p < 0.001)." (PMID 40370439, 2025). "Through single-cell transcriptome analysis, we revealed the simultaneous state of activation and exhaustion in CD38+HLA-DR+ T cells in COVID-19." (PMID 40370439, 2025). "We observed a significant increase in CD38 expression in COVID-19 patients, particularly those with severe disease." (PMID 39852780, 2024). "Several investigations have found that the number of switched (e.g., CD27 on IgD- CD38br) and unswitched (e.g., CD19 on IgD+ CD38-) memory B cells is significantly reduced in COVID-19 patients." (PMID 39224704, 2024). "The data also indicated a higher percentage of mature naive B cells (MN) (CD27−, CD38+), antibody-secreting plasmablasts (CD27+, CD38+), and resting memory B cells (RM) (CD27+, CD38−) in COVID-19 patients compared with healthy individuals." (PMID 39407725, 2024). "Studies have shown that CD38 expression on immune cells, such as T cells and monocytes, is elevated in COVID-19 patients, particularly in acute and critically ill individuals." (PMID 39852780, 2024).
COVID-19 (continued). "Although some studies have reported even more long-term immune perturbations in patients following COVID-19 recovery, these alterations are generally infection-related signatures, such as CD38+HLA-DR+ T cells and CXCR3 expression." (PMID 38429462, 2024). "They reported that activation of T cells, demonstrated by the CD38 expression, was evident for patients with acute COVID-19, which is comparable to the results of previous studies." (PMID 36675642, 2023). "This is in line with several studies trying to understand the immune profile of COVID-19 patients that report elevated frequencies of CD38+ ICOS+ CXCR5+ CD4+ T cells during acute disease." (PMID 37061513, 2023). "Concomitantly, as compared to COV patients, we report that COV/CA patients have higher frequency of activated HLA-DR+ and CD38+/HLA-DR+ T cells, which is in line with enhanced COVID-19 severity." (PMID 37063865, 2023). "Conversely, hospitalized COVID-19 patients > 70 years of age showed increased blood plasmablast B cells (CD19low, CD20-, IgD-, IgM-, CD80+, CD38+), compared to hospitalized COVID-19 patients < 60 years of age." (PMID 36941580, 2023). "These patients face a dual challenge as those most likely to have a poor vaccination response, such as those on anti-CD38 or anti-BCMA-based therapies, are also at the highest risk of developing severe COVID-19." (PMID 37509261, 2023). "Ultimately, CD38, as an orchestrating immune-modulatory enzyme, provides a potential target involved in COVID-19 pathogenesis." (PMID 36675642, 2023). "In general, comparing the healthy control group with COVID-19 patients, the results showed that there was a significant difference in the count of cells expressing CD38+, and severe patients’ count was the lowest." (PMID 36675642, 2023). "The anti-SARS-CoV-2 antibody titer relation with the components of cellular immunity (CD3+ cells and CD8+/CD38+ ratio) shows a role of both chains during the response to the COVID-19 vaccine in kidney transplant patients." (PMID 36839623, 2023). "CD8+ T cells followed a prototypical activation pattern during acute COVID-19, with a significant increase in HLA-DR+CD38+ CD8+ T cells and granzyme and perforin expression." (PMID 37036008, 2023). "An increase in HLA-DR and CD38 expression levels has been reported by us in T lymphocytes in severe and moderate cases of COVID-19." (PMID 37240393, 2023). "Therapeutics targeting the CD38/NAD+ axis were highlighted as key options to improve COVID-19 patients’ outcomes." (PMID 36675642, 2023). "The present study aimed to highlight the role of monitoring T cell subtypes and their activation (expression of CD38) in COVID-19 patients compared to healthy subjects and their role in predicting severity and patients’ outcomes." (PMID 36675642, 2023). "Compared to HCs, COVID-19 patients were characterized by a low level of central memory T4 cells and high percentages of activated (CD38+ and HLA-DR+CD38+) and exhausted (PD-1+) T4 cells." (PMID 38235145, 2023). "Several studies have reported an activated phenotype of CD8+ T cells in patients with severe COVID-19, characterized by an increased expression of CD38 or/and HLA-DR molecules." (PMID 37240393, 2023). "In the presented study, T cell subtypes and the expression of CD38 was assessed and correlated to the severity of COVID-19 and patients’ outcomes." (PMID 36675642, 2023). "The aim of this study is to highlight the role of monitoring T cell subtypes and their activation (expression of CD38) in COVID-19 patients compared to healthy subjects and their role in predicting severity and patients’ outcomes." (PMID 36675642, 2023). "Our data are in accordance with others showing increased levels of CD38+CD8+ T cells in the viral clearance phase of COVID-19 patients." (PMID 35265078, 2022).
COVID-19 (continued). "Expression of PD1, ICOS, and CD38 were similar between COVID-19-naïve individuals with PAD syndromes and healthy donors at day 7 to 28 following vaccination, suggesting there was no defect in CD4+ T cell activation in most individuals with PAD syndromes." (PMID 36618402, 2022). "At the protein level, NK cells from COVID-19 patients had elevated expression of activation markers (e.g. CD38 and CD69), cytotoxic proteins, such as perforin, and the death receptor ligand FasL." (PMID 35284964, 2022). "For all non-naive CD4 T-cell subsets (primarily for EM1, EM2, and EM3), an increased number of both CD38+HLA-DR+ and also Ki-67+ cells were found in patients with COVID-19." (PMID 35632823, 2022). "We observed subtle differences in induction of ICOS+CD38+ cTfh following vaccination based on prior history of COVID-19." (PMID 34874183, 2022). "In circulating T cells, both CD4+ and CD8+ T cells in the patient with myopericarditis after COVID-19 vaccine exhibited an activated phenotype defined by CD38+HLA-DR+ and PD-1+Ki-67+ compared to healthy and vaccine control groups." (PMID 35251049, 2022). "The R848-treated myeloid populations from COVID-19 patients also showed reduced expression of HLA-DR and enhanced expression of CD38, CD68, CD80, and CD206, which was similar to the untreated condition." (PMID 36085197, 2022). "The percentage of CD8+CD38+HLA-DR+ T cell population was significantly higher in the peripheral blood of COVID-19 patients (23.5%), compared to HS (6.5%) and VS (6%) groups (p<0.001)." (PMID 35898494, 2022). "Another study showed that the proportion of PD-1+ICOS+ and CD38+HLA-DR+ cells increased within the CXCR5+CD4+ Tfh pool in the circulation in all patients with COVID-19." (PMID 35632823, 2022). "In particular, it was shown that a bronchoscopy of critically ill COVID-19 patients requiring invasive mechanical ventilation (IMV) detected a great quantity of activated CXCR5 co-expressing CD38+CD8+ T cells." (PMID 36146713, 2022). "In relation to COVID-19, it was shown, that two different subpopulations of CD8+CD38+HLA-DR+ cells are present in COVID-19 patients." (PMID 35392095, 2022). "Recently, many associations with endothelial dysfunction and NAD+ deficits, as well as CD38 activity, in the development of COVID-19 have also been demonstrated." (PMID 35625403, 2022). "According to a more detailed analysis of T cell subpopulations in severe COVID-19 patients the HLA-DR+CD38+CD8+ T population consisted of two diverse subsets with distinct characteristics: HLA-DR+CD38dim and HLA-DR+CD38hi." (PMID 35630492, 2022). "The increase in HLA-DR and CD38 expression associated with activation of CD8 and CD4 T cells in critical COVID-19 patients has already been found in association with an increased frequency of terminally differentiated EMRA CD4+ and CD8+ cells." (PMID 35425776, 2022). "The fraction of CD38+HLA-DR+ activated CD4+ T cells in the COVID-19 patients significantly decreased over the study duration and appeared to be lower than healthy controls at 6-7 months although this was not significant." (PMID 36003367, 2022). "In agreement, we found a marked expansion in the frequency of activated T cells (expressing CD71, CD38, and HLA-DR) in COVID-19 patients." (PMID 35284964, 2022). "On the other hand, COVID-19 patients show specific CD8+ T cell subsets expressing HLA-DR+CD38+PD-1+." (PMID 36369012, 2022). "As for the activation markers, the level of CD38 and HLA-DR expression increased on T-helpers of the peripheral blood of COVID-19 patients, with the maximum values of CD38+HLA-DR+ cells found in severe cases." (PMID 35632823, 2022). "After applying FlowSOM to cluster cell types, we discovered a HLA-DR+ CD38+ CD8+ T cell whose %parent is greater in COVID-19 patients than healthy controls (p = 3.19 × 10−10, FDR = 2.76 × 10−8)." (PMID 34844647, 2021).
COVID-19 (continued). "A significant increase of peripheral hyperactivated HLA-DR+CD38+ CD8+ T cell expressing CD45RO+ memory phenotype in some convalescent severe patients is interesting considering its oblivion during active severe COVID-19." (PMID 34867943, 2021). "In a cohort of critical COVID-19 patients with hypertension, the percentage of CD38+HLA-DR+ fraction among CD8+ T cells was higher in the patients with fatal outcomes compared with the surviving patients." (PMID 34567001, 2021). "Our above observation suggested that CD8+ CD38+ cell responses in COVID-19(+) patients were similar to other viral infections." (PMID 33419040, 2021). "Memory cells (CD27+CD45RA-) that express PD-1 and CD38 (Pop0) and PD-1, CD38 and HLA-DR (Pop2), as well as CD27-CD45RAlow expressing PD-1, CD38 and HLA-DR (Pop6) were also expanded in COVID-19 patients." (PMID 33777054, 2021). "Circulating plasmablasts and CD8+HLA-DR+CD38+ activated T cells expanded earlier and in higher numbers than in more severe COVID-19 groups, most notably in the first week after symptom onset." (PMID 34051148, 2021). "In the COVID-19(+) there was a lower proportion of CD4+ CD38+ cells than in the other groups (significant differences between COVID-19(+) and COVID-19(−) virus groups)." (PMID 33419040, 2021). "Our observation of the decline of CD38+ CD4+ cell population in COVID-19(+) patients relative to other infections was shown here for the first time." (PMID 33419040, 2021). "RE-LYMP correlated with activated T lymphocytes CD38+ and HLA-DR+ in the COVID-19(−) virus group, however in the COVID-19(+) group correlations with T lymphocytes CD25+ and CD45RO+ were observed." (PMID 33419040, 2021). "We observed enrichment of the megakaryocyte progenitor signature in the CD38+ HSPC populations in moderate COVID-19 compared to the healthy condition, but no enrichment of erythroid or myeloid signatures in either CD38− or CD38+ HSPCs." (PMID 33879890, 2021). "These contradictory results of CD38+HLA-DR+ CD8+ T cells in COVID-19 patients implied the heterogeneity of this population, which was supported by our findings." (PMID 34567001, 2021). "Severe COVID-19 patients showed a significant increase of HLA-DR+CD38+ CD8+ T cells compared to mild cases." (PMID 34567001, 2021). "A higher frequency of CD38+ cells in MIS-C compared to pediatric COVID-19 was also observed for MAIT cells." (PMID 33653907, 2021). "COVID-19 patients displayed an immune phenotype characterized by increased HLA-DR+CD38+ and PD-1+ CD4+ and CD8+ T cells, and elevated CD8+CD244+ lymphocytes, compared to healthy controls." (PMID 33717195, 2021). "The subsets showed a significant association with the inflammatory status in COVID-19, especially with regard to increased neutrophils, T-killer, T-active, T-suppressor, and T-CD8+CD38+ in individuals belong to the either COVID-19 and Covid-like NP group." (PMID 34683357, 2021). "Secondly, altered hematopoiesis is evident in the peripheral circulation with megakaryocyte-primed gene expression in the earliest CD34+CD38+ HSPCs, and expanded megakaryocyte progenitors in the response to COVID-19." (PMID 33879890, 2021). "It seemed that the effects of CD38+HLA-DR+ CD8+ T cells in COVID-19 patients varied widely in different studies." (PMID 34567001, 2021). "In the COVID-19(+) we noticed a lower median proportion of CD4+ CD38+ cells than in the HC group and COVID-19(−) virus group (significant differences between COVID-19(+) and COVID-19(−) virus group, (respectively 11.0% vs. 23.0%, p < 0.05)." (PMID 33419040, 2021). "Although COVID-19 patients did develop severe lymphopenia in response to T cell exhaustion, an elevated proportion of HLA-DR+CD38+ CD8+ T cells suggests a potent adaptive immune response in these patients." (PMID 34567001, 2021). "We observed that COVID-19 patients exhibited a significant expansion of activated (CD38+HLA-DR+) cells, especially in the patients with severe disease." (PMID 33777054, 2021).
COVID-19 (continued). "These high frequencies of activated HLA-DR+CD38+ T cells together with HLA-DR+ and CD69+ activated CD56dim NK cells were associated with acute COVID-19 and decreased with recovery in CONV." (PMID 34893580, 2021). "We have also analyzed the DN T cells, and in a similar way to what happens with CD4 and CD8 T cells, the activated (HLA-DR+CD38+) and perforin expressing DN T cells are significantly expanded in COVID-19 patients." (PMID 33777054, 2021). "Recently, it has been shown that the frequency of CD38+ HLA-DR+ CD8 T cells was elevated in COVID-19 patients who had a concomitant infection with other pathogens but were not impacted by pre-existing immunosuppression or treatment with steroids." (PMID 34197543, 2021). "Despite heterogeneity in the range of Ki67+ or HLA-DR+CD38+ cells, proliferation and activation were positively correlated in both pediatric COVID-19 and MIS-C." (PMID 33653907, 2021). "We detected a strong activation profile of SARS-CoV-2-specific T cells only in COVID-19 patients, and this strong activation signature (high expression of CD38, CD39, PD1, HLA-DR) was further enhanced in patients requiring hospitalization." (PMID 33853928, 2021). "Assessing the phenotypical profile of SARS-CoV-2–specific CD4+ T cells, the following trends were observed in less severe forms of COVID-19 (WHO 4 or lower): increased expression of CD38, Ki67, and GrB and reduced expression of HLA-DR." (PMID 33945513, 2021). "Compared to both healthy donor cohorts, we observed that more SARS-CoV-2-reactive T cells from COVID-19 patients expressed the activation markers CD38, CD39, CD69 and HLA-DR, and showed a late-differentiated effector memory profile of reduced CD27." (PMID 33853928, 2021). "The CD20dim/− PB populations of COVID-19 patients also encompassed more CD27+CD38+ cells as compared with recovered patients or healthy individuals (HD)." (PMID 34723157, 2021). "Nevertheless, little is known about phenotype and function of CD38+HLA-DR+ CD8+ T cells and association with clinical outcome in COVID-19 patients." (PMID 34567001, 2021). "Earlier studies have also reported a high frequency of CD38+HLA-DR+CD8+ T cells in uncomplicated COVID-19 cases (compared to healthy control) and resolved severe cases (compared to severe persistent cases)." (PMID 33808906, 2021). "During analysis of the CD38+ marker on CD4+ cells we observed that there were lower CD4+ CD38+ cells in COVID-19(+) patients compared to the HC group and COVID-19(−) virus group." (PMID 33419040, 2021). "In this study especially the frequency of CD38+HLA-DR+ CD8 T cells was elevated in COVID-19 patients who had a concomitant infection with another pathogen but was not impacted by pre-existing immunosuppression or treatment with steroids." (PMID 34197543, 2021). "MAIT cells from COVID-19 patients expressed significantly higher levels of the activation markers CD38, CD69 and HLA-DR, as well as of the exhaustion markers CTLA-4 and PD-1, compared to healthy controls." (PMID 33546489, 2021). "Higher levels of CD38 were detected specifically in moderately sick COVID-19 patients, while the maturation markers HLA-DR and CD86 were decreased over all DC subsets (with an exception for DC1s) in severe disease." (PMID 33479167, 2021). "There is a growing body of evidence that circulating CD8+ T cells from patients with severe COVID-19 exhibit an activated phenotype characterized by increased expression of CD38, HLA-DR, and Ki-67." (PMID 34413488, 2021). "In a longitudinal analysis, we found that the expression of PD-1 and CD38 in MHC-I multimer+ cells decreases during the course of COVID-19." (PMID 34413488, 2021). "Cytotoxic CD8+ T cells from severe COVID-19+ donors also had an increased proportion of cells expressing CD38 or co-expressing PD-1 and CD38 compared to HD (p=0.0082)." (PMID 32669287, 2020). "The activation markers CD69 and HLA-DR/CD38 were elevated on T cells in COVID-19 and malaria patients." (PMID 32983106, 2020).